CD4 (CD4 molecule)
Diseases named in the same sentence as CD4 in open-access papers (continued):
Sharing a sentence is not in itself a finding about the gene and the disease.
infection (continued). "Whether or not this is reminiscent of human infection is unclear, but it does suggest that in the transcervical mouse model of C. trachomatis inoculation, there are localized inflammatory pockets within the genital tract that contain both host T cells and antigen-specific CD4+ T cells." (PMID 32184237, 2020). "After infection, the serum AST concentrations remained normal in HHD mice lacking both CD4+ and CD8+ T cells, while the AST concentrations elevated in HHD mice." (PMID 32155851, 2020). "At the same time point post-infection, we also found that expression of the activation marker CD69 was upregulated on CD4+ T cells in the lungs of WT but not Il17a-KO mice." (PMID 32636457, 2020). "After infection, the percentage of CD3+CD4+ and CD3+CD8+ lymphocyte from normal, PBS/FCA and PBS groups was 11.24% and 8.12%, 14.81% and 9.67%, 14.75% and 9.94%, respectively." (PMID 32176727, 2020). "Over the course of infection, the percentage of CD8+, but not CD4+, T cells expressing CD103, a marker for TRM cells in the brain, increased." (PMID 31963302, 2020). "Mycobacteria-specific resident memory CD4 and CD8 T cells (TRM) expressing PD-1 accumulated in the lung after aerosol infection and intratracheal (i.t.)-but not subcutaneous (s.c.)- BCG immunization." (PMID 33193338, 2020). "After initial infection and during chronic disease, there was an increase in non-classical monocytes, NK and NKT cells while the CD4:CD8 T cell ratio inverted from a 2:1 to 1:2.5." (PMID 32154190, 2020). "Julg reported data indicating that CD4+ T cells from ECs are easily infected with HIV ex vivo, which suggests that these cells are not resistant to infection and that the virus isolated from these individuals exhibits competent replication." (PMID 32711474, 2020). "In another study, it is observed that CD4 + T cell mediated antibody response, but not CD8 + T cells, was essential for viral clearance in intravaginal infection model." (PMID 32265852, 2020). "In summary, we have demonstrated enhancement of PD-1 expression on BVDV-infected CD4+ and CD8+ T cells, but not B cells, following infection with CP BVDV and NCP BVDV in vitro." (PMID 32256500, 2020). "The CD4 receptor is not commonly expressed within the NK lineage, but infection with human herpesvirus 6 (HHV-6, family Herpesviridae) can upregulate CD4 expression in NK cells." (PMID 30870969, 2019). "We sought to examine the expression of canonical HIV binding receptor CD4 and co-receptor CCR5 on different monocyte subsets as a potential contributing factor to varying disease states including non-progressive infection that was accompanied by viremia." (PMID 31867010, 2019). "Furthermore, it was recently demonstrated that macrophages could sustain HIV replication in vivo in the absence of T cells, supporting the hypothesis that macrophages are a primary target of HIV and may help transmit the infection to other cell types even in the absence of CD4+ T lymphocytes." (PMID 30850623, 2019). "Second, all the study participants were HIV-1 infected participants, and lacked some clinical information (CD4-cell counts, HIV-1 viral load, etc.)and duration of infection." (PMID 31023332, 2019). "pDCs are also known to produce IFN-III in response to HIV, which can exert antiviral effects in infected CD4+ T cell how this formally contributes to HIV transmission and early infection is not known." (PMID 31156637, 2019). "Given that this study measured CD4 count at less than 200, our findings indicate advanced HIV level of infection progression and its negative impacts on QoL." (PMID 31665007, 2019). "We did not see any correlation between the estimated length of infection and frequency of class II-restricted CD8+ T cells or correlation between CD4+ T cell count and frequency of class II-restricted CD8+ T cells." (PMID 31308388, 2019).
infection (continued). "The first phase of transfer is not dependent of productive infection, but rather on CLR mediated endocytic uptake, and occurs within 2 h and then declines rapidly with time until 24 h post exposure when no transfer to CD4 T cells is observed." (PMID 31227717, 2019). "Whilst it is clear that CD4+ T cells are the primary substrate of HIV, not all subsets are equally permissive to infection and each subset can have very different outcomes when infected." (PMID 31156637, 2019). "An additional potential mechanism responsible for CD4 T cell repertoire editing, particularly after infection, are the possible negative effects of robust IFN-γ production on priming and expansion of new CD4 T cells." (PMID 31134060, 2019). "We did not use the QVOA since human resting CD4+ T cell numbers were too low to produce enough infectious virions after LRA treatment after MOLT-4-CCR5 propagation and TZM infection." (PMID 30716099, 2019). "Analysis of lymphocyte subsets via flow cytometry showed that CD4+ T cell, CD8+ T cell, and natural killer cell counts were lower among those with CMV disease compared to those with CMV viremia and those without infection." (PMID 31574798, 2019). "However, since the main targets of HSV1 are the skin epithelium cells and neurons, this clonal extinction might lead to an uncontrolled infection only sustained by the cytotoxic action of other effector immune cells that do not require any helping signals from the CD4+ T cells." (PMID 31824487, 2019). "Surprisingly, in these experiments we did not see the expected increases in CD4+ and CD8+ T cell populations in the brain of WT mice during infection." (PMID 31015511, 2019). "In comparison, no significant increase of Ki67+ in CD4+ and CD8+ T cells was observed in mice after CMCC50115 infection." (PMID 30898022, 2019). "After 26 days of infection, 4160::Tn showed attenuated growth in both the liver and spleen, though the MAH-specific effector CD4+ T cell response was not significantly reduced." (PMID 31822597, 2019). "TLR stimulation did not induce significant CD4+ T cell activation compared to the unstimulated control (p > 0.05) at day 3 (post stimulation, prior to HIV infection) or day 5 (post infection)." (PMID 31396221, 2019). "It has been reported that though antigen-specific CD4 T cells and IFN-γ are important for controlling M. tb infection, they are not sufficient for protecting against the infection." (PMID 31130711, 2019). "Polyfunctional CD4+ T cells were also identified in individuals submitted to a DENV-1 vaccine candidate, although protection against infection was not investigated in this particular study." (PMID 30761131, 2019). "While ART consistently improves patient CD4/CD8 ratio, irrespective of pre-ART CD4+ counts, CD8+ T cell absolute counts in untreated infection remain relatively stable post-ART." (PMID 30863403, 2019). "We observed no reduction in the frequency or absolute cell numbers of peritoneal CD4+IFN-γ+ T cells in the absence of NLRP3, ASC, or Casp1/11 by day 8 post-infection." (PMID 31194844, 2019). "Now, we compared the migration capacity of different subpopulations of naive T cells, (CD3+, CD4+, and CD8+ T cells) in presence or absence of the chemokine CXCL12 and/or E-30 infection." (PMID 31752904, 2019). "In particular, they showed that CD4+ T cells were required for the production of ZIKV-specific IgG, but not for viral clearance during either primary or secondary infection." (PMID 30677097, 2019). "In comparison with HC, the absolute number of CD3+T cells, CD4+T cells, CD8+T cells, NK cells, and NKT cells were significantly down-regulated in SLE patients with and without infection (all P<0.05)." (PMID 30994732, 2019). "Unlike CD4+, the total CD8+ T cell numbers were significantly higher at 14- and 150-days post infection in VEH/SIV compared to THC/SIV rhesus macaques." (PMID 31114576, 2019).
infection (continued). "For a long time, it was considered that, unlike T lymphocytes CD4+, T lymphocytes CD8+ had no role in controlling the infection and Mtb disease." (PMID 31508399, 2019). "In the current study, the differences in CD3+, CD4+, CD8+, and CD4+/CD8+ were not obvious among the three treatments, both 3 and 7 days post-infection." (PMID 29948799, 2019). "After infection of chickens, MDV can be detected in both immune and nonimmune cells; however, the virus can only be detected in less than 2% of CD4+ T cells in the spleen." (PMID 30971474, 2019). "The mean frequencies of CD4+ PFC against lytic and latent cycle antigens did not change significantly over time from primary infection to long term persistent stage." (PMID 29599759, 2018). "A negative correlation confirmed that as more CD4+ cells, lesser CD4+Foxp3+ cells in the lungs of CCR4−/− mice, but not WT mice, at 70 days of infection." (PMID 30584243, 2018). "Patients 103_co and 107_co have asymptomatic infection by HIV and no detectable HIV viral load, CD4 count cell or transmission path." (PMID 29844604, 2018). "Overall, our data suggest that the accumulation of inhibitory receptors on CD4+ T cells is increased in HIV-infected subjects also on long-term cART, but not in subjects naturally controlling the infection." (PMID 29403500, 2018). "Not surprising, the numbers of CD4+ and CD8+ cells remained similar to naïve mice, without any statistically significant difference between young and old mice at this stage of infections." (PMID 30619263, 2018). "Further analysis indicated the increased trend of KUL01+, IgM+ B, CD4+ and CD8+ cell subsets in CpG DNA treated/ILTV infected chicken lungs at 6 days post-infection when compared to that observed in non-CpG DNA treated/ ILTV infected chickens." (PMID 29513732, 2018). "Although a distinct population of NKT cells (CD4+ TCR-βintNK1.1+) was present in the spleen of naïve WT mice, this population did not expand during infection." (PMID 30374346, 2018). "Significantly higher levels of HIV RNA were detected in myeloid cells in the cervix after infection with JRCSF-Vpx than with WT JRCSF (p = 0.02, paired t-test), but the amount of HIV RNA did not significantly differ in CD4+ T cells (p = 0.78)." (PMID 30532754, 2018). "Strikingly, we found that the infection with HeV and NiV-B did not modify the expression levels of lymphocyte markers (CD2, CD3D, CD3E, CD3G, CD4, CD8A and CD27) in the lung tissue by 5 dpi." (PMID 29538374, 2018). "Mice in the PBS mock vaccination group, no matter whether treated with PBS, CD4 depletion antibody or CD8 depletion antibody, showed continuous weight loss after A(H1N1)pdm09 challenge (PBS) and displayed the same virus titers in lung tissue on day 6 post-infection (PBS)." (PMID 30356772, 2018). "CD4+ T cells were capable of expressing PD-1, B cell lymphoma 6, and CXCR5 during early infection, indicating TFH development was not impaired." (PMID 30631323, 2018). "Although the addition of EBOV to isolated T lymphocytes does not result in a productive infection, EBOV virions have recently been shown to directly bind to and activate CD4+ T cells." (PMID 29649305, 2018). "Despite having comparable CD4 and chemokine receptor expressions, CD62L KD #8 and #32, but not clone #3 were more resistant to HIVLAI infections than their parental CEM cells." (PMID 30026537, 2018). "The infection rate in CVC HD is not more frequent in HIV-infected patients, provided that CD4+ count is ≥ 200 cells/μL and the patient is virologically suppressed." (PMID 30568839, 2018). "To determine the responsiveness of T cell in T. spiralis-infected mice, we examined the CD4+ T cell proliferation upon non-specific (anti-CD3/anti-CD28) and antigen-specific stimulation in WT and PD-1−/− mice with or without infection." (PMID 30093899, 2018).
infection (continued). "We also observed a negative correlation between time since infection and total HIV DNA in CD4+ T cells from the slow progressors, although this was not significant due to the few patients included." (PMID 30323326, 2018). "People infected with S. japonicum had a slightly higher level of CD4+ T lymphocyte counts and a lower level of CD8+ T lymphocyte counts compared with people with no infection, but these were not statistically significant." (PMID 30057918, 2018). "Tissue-resident memory T cells (Trm) are a population of non-circulating CD4+ and CD8+ T cells that stay in peripheral tissues after infection to build a rapid first-line defense against recurring pathogen invasion." (PMID 30038627, 2018). "In an attempt to understand better the preferential infection of TFH cells, we performed microarray analysis on TFH (CD4+CXCR5high) and non-TFH (CD4+CXCR5low) T cells sorted from lymph nodes from healthy subjects (not published data)." (PMID 29967602, 2018). "Our data confirm that primary CD4+ T lymphocytes coinfected with HIV-1 and HTLV-1 were able to transmit HIV-1 to FLGTECs and initiate productive infection of these cells that are normally nonpermissive to HIV-1." (PMID 29624497, 2018). "As shown in, our data indicated that on day 7 post infection, CXCR3−/− mice had significantly less amount of CD4 T cells in Spl and iLN, but not in GT, than WT." (PMID 29552679, 2017). "The expression of HEL had no impact on the extent of splenic T cell proliferation, since similar CFSE profiles and HEL-specific CD4+ T cell numbers were observed in non-transgenic (nTg) control mice and sTg-IRBP:HELhi mice after infection with MCMV-HEL." (PMID 29079770, 2017). "In contrast, large numbers of proliferating HEL-specific CD4+ T cells were detected in the retinas of sTg-IRBP:HELhi mice on day 4, peaking 7–10 days post-infection (days post infection not significant; nTg vs sTg, p = 0.0007)." (PMID 29079770, 2017). "Whether this requires a pre-existing population of target cells in the tissue, or if recruitment of CD4+ target cells following induction of host innate immunity, pro-inflammatory cytokines, and inflammation at the site of transmission is necessary for successful infection, is not clear." (PMID 29127409, 2017). "In TBLN and tonsils, CD4+ T cells of only a few infected animals responded with IL-17A production to APP-CCE stimulation, regardless of the time post infection." (PMID 28166835, 2017). "In our study, we found that the CD4+ cell number and the CD4+/CD8+ ratio were lower in SLE patients with infection than in those without infection." (PMID 29267496, 2017). "The HIV-1JR-FL Env(+)Δ712 FT glycoprotein did not detectably support virus entry into Cf2Th-CD4/CCR5 cells in this assay, whereas the Env(+)Δ712 FTmut glycoprotein mediated infection at a level 37% of that observed for the Env(+)Δ712 glycoprotein." (PMID 28209172, 2017). "Interestingly, the absolute numbers of IL-10-producing CD4+ cells in infected TSLPR−/− mice were higher than those from WT mice on day 45, and this could be explained by the higher hepatosplenomegaly observed during the late stage of infection in TSLPR−/− mice." (PMID 28769924, 2017). "Contrary to these findings it was seen that depletion of CD4+ and CD8+ T cells in Syrian hamster before infection did not lead to lethality when infecting with ANDV." (PMID 29077702, 2017). "At 3 days post-of-infection (dpi), CBL0100 alone moderately decreased the p24 level in the supernatant of HIV-infected CD4+ T cells across the three donors tested, without any cytotoxicity." (PMID 29089933, 2017). "Our studies centered on CD4+ T cells because we and others have previously identified CD4+ T cells, but not CD8+ T cells, to be critical for control of L. donovani growth during primary infection." (PMID 29075269, 2017).
infection (continued). "In vitro, T cell recognition of BLLF1/BALF4/BZLF1 epitopes did not require productive infection, could occur in the context of viral transfer to bystander B cells and was capable of controlling proliferation of infected B cells via cytolysis, further confirming the therapeutic potential of CD4 CTL." (PMID 28167943, 2017). "The percentage of sequestered cells that were CD4+ or CD8+ T cells was not affected by bpV(phen), but infection reduced the percentage of CD4+ T cells and increased the percentage of CD8+ T cells." (PMID 28710387, 2017). "IL-17A was predominantly secreted by γδT cells (especially the Vγ4+γδT subset), but not CD4+Th and CD8+Tc cells at the early stage of infection, and IL-1β and/or IL-23 were sufficient to induce IL-17A production by γδT cells." (PMID 28912779, 2017). "In contrast, here, we show that the absence of CD30 alone does not appear to impact CD4, CD8, or Treg responses in these two infection models." (PMID 28993768, 2017). "Although the duration of HIV infection for our study participants was not known, their well-maintained CD4+ T-cell counts in the absence of ART (median, 619 cells/mm3) likely reflected relatively early infection." (PMID 29029171, 2017). "A comparison of the infected and mock-infected WT and TLR2/9−/− groups showed that the overall production of perforin in the TG by several cell types (such as CD4+, CD8+, NK T and NK cells) was not statistically significant during infection." (PMID 28222752, 2017). "To determine the stage of the infection block, we infected HALUC-expressing (negative control) or HASUN1-expressing U87MG CD4/CXCR4 cells with the VSV-G-pseudotyped HIV-1 GFP LV and isolated total DNA at various time points postinfection." (PMID 28747499, 2017). "In an infection model that requires little CD4, a reduced CD4 affinity would pose no great fitness penalty: conceivably, any additional surface CD4 density beyond a certain threshold level could help promote infection, but this excess CD4 would not be strictly required." (PMID 28122636, 2017). "Our results show that, in the lungs of infected mice, the percentage of γδT cells, but not the percentages of CD4+Th and CD8+Tc cells, gradually increased and peaked at 3 days post-infection (dpi)." (PMID 28912779, 2017). "With the recently released WHO guidelines recommending ART initiation regardless of CD4+T cell counts to all HIV-infected individuals, it is expected that the number of people living with the infection will increase worldwide by improving their survival." (PMID 28575010, 2017). "First, the interaction between viral envelope protein, gp120, and murine surface receptors, CD4 and CCR5, does not lead to infection in the mouse cells." (PMID 29259541, 2017). "In contrast to littermate control BALB/c mice, which developed ulcerating, necrotic lesions following infection with L. major LV39 and IL81, lack of IL-4-responsive CD4+ T cells led to a healing phenotype similar to that of the resistant C57BL/6 mice." (PMID 29176972, 2017). "To investigate the changes in the earliest thymocyte precursors gated as DN population lacking CD4 and CD8, we analyzed the CD44 and CD25 expression profiles upon infection." (PMID 28091621, 2017). "CCR5–CCR3 and CCR5–CCR2b chimeras, expressed in Ghost cells carrying human CD4 but not CCR5, showed significantly (p < 0.001) impaired capability to support JRFL infection, achieving less than 50% efficacy of WT CCR5." (PMID 28484468, 2017). "Lung CD4+ IFN-γ producing T cells (i.e., T cells of the Th1 lineage) were unchanged at 24 hours in either ethanol-treated or control groups with and without infection in our model." (PMID 29348965, 2017). "Again, no CD4 T cell responses were detected in these cultures, suggesting the specific stimulation of CD8 T cells following infection." (PMID 28484224, 2017).